CENPVL1 (centromere protein V like 1)
Synonyms: CENPVP1; PRR6L1
Gene: Protein-coding gene on chromosome X (51,710,512 to 51,712,131, forward strand). Ensembl gene ENSG00000223591.
Gene Ontology:
Molecular function: carbon-sulfur lyase activity
Homologues: Orthologues: chimpanzee CENPVL1 (99% identical), chimpanzee CENPVL2 (99% identical), macaque CENPVL3 (94% identical), tropical clawed frog cenpv (39% identical), zebrafish cenpv (29% identical), Caenorhabditis elegans F25B4.8 (19% identical). Paralogues in human: CENPVL2 (100% identical), CENPVL3 (96% identical), CENPV (51% identical).
Diseases named in the same sentence as CENPVL1 in open-access papers:
CENPVL1 is named in the same sentence as 3 diseases in open-access papers, as found by Europe PMC text mining. Sharing a sentence is not in itself a finding about the gene and the disease.
CENPVL1 shares sentences with these, for which no sentence is quoted: developmental delay (1 paper); Intellectual disability (1); X-linked intellectual disability (1).